INS (insulin)
Diseases named in the same sentence as INS in open-access papers (continued):
Sharing a sentence is not in itself a finding about the gene and the disease.
Obesity (continued). "The purpose of this narrative review is to describe the mechanisms responsible for the development of infertility and PCOS, with a focus on the role of obesity, insulin sensitivity and treatment with metformin and GLP-1s." (PMID 38540265, 2024). "Our model demonstrated significant increases in food intake and body weight, along with markedly reduced insulin levels and significantly elevated fasting blood glucose levels, effectively replicating key features of obesity and T2DM." (PMID 39458511, 2024). "In obesity, plasma insulin increases with glucose levels due to the heightened insulin secretion, paired with decreased insulin clearance." (PMID 38248845, 2024). "It is worth mention here that ILC2s serve as key determinants of diet-induced obesity and can positively influence insulin resistance in the adipose tissue, thus limiting the severity of MetS." (PMID 39200288, 2024). "DM is characterized by four metabolic abnormalities: impaired insulin production, elevated endogenous glucose, aberrant insulin action, and obesity." (PMID 39599599, 2024). "In human and rodent studies, Bifidobacterium is a beneficial bacterium for the prevention of obesity and metabolic diseases, as it reduces blood sugar levels, induces insulin secretion, and improves endotoxemia." (PMID 39272309, 2024). "Obesity is the most important risk factor for T2DM, which is characterized by chronic hyperglycemia, insulin resistance, and inefficient insulin secretion and action." (PMID 38732046, 2024). "On the contrary, fasting C-peptide was markedly upregulated in people with obesity (3.6 ± 1.04 ng/mL vs. 1.88 ± 0.49 ng/mL likewise; p < 0.001), potentially indicating a milieu of increased insulin resistance." (PMID 38762719, 2024). "An important scientific finding is that PIEZO1 plays a central regulatory role in insulin sensitivity, glucose metabolism and energy expenditure in obesity." (PMID 39519393, 2024). "Obesity leads to abnormal hormonal responses during gestation, such as increased levels of leptin, insulin, and insulin-like growth factor (IGF), which influence fetal development." (PMID 39690358, 2024). "AMPK activation has been reported to promote the translocation of the insulin-sensitive GLUT4 pool, which would enhance insulin action independently of changes in insulin signal transduction and should be further explored in individuals with obesity." (PMID 38324260, 2024). "As a result, in case of obesity, insulin and GLP-1RA inhibits physiological glucagon functions while GLP-1RA stimulates insulin secretion disbalancing the equilibration of fasting/postprandial state." (PMID 38579770, 2024). "This compound has shown a 30% improvement in hepatic and muscle insulin sensitivity in people with obesity compared to the placebo." (PMID 39056692, 2024). "Children with obesity also exhibited elevated fasting insulin levels and HOMA-IR scores, changes that were more pronounced among subjects with PO." (PMID 38238301, 2024). "As the levels of obesity are increasing on a global level, its effects on human health due to dysregulated lipid, glucose, and insulin metabolism, together chronic low-grade inflammation and oxidative stress, are becoming more and more significant." (PMID 38891115, 2024). "Mean energy intake and fat mass were greater for individuals on the LCD, findings interpreted as opposing the carbohydrate–insulin model (CIM) of obesity." (PMID 38128881, 2024). "These adaptations include increased mitochondrial activity and content, enhanced insulin sensitivity and glucose uptake, and reduced inflammation, all of which are impaired in obesity." (PMID 38981607, 2024). "In the intestinal MCT1-deficient mice, we discovered sex-dependent alterations in glucose tolerance/insulin sensitivity, diet-induced obesity, transport of monocarboxylate including lactate and SCFAs, local and systemic inflammation, and gut microbiota." (PMID 39871878, 2024).
Obesity (continued). "Resistin inhibits the ability of insulin to stimulate cellular glucose uptake and links obesity to insulin resistance." (PMID 39045929, 2024). "In contrast, RA supplementation in males with obesity (approximately 1% of energy intake for 12 weeks) reduces insulin sensitivity compared to placebo, thus raising concerns about the impact of RA on metabolic health." (PMID 39272602, 2024). "Many studies report findings on the relationship between BCAA blood levels and age-related changes in body composition, physical function, sarcopenia, obesity, insulin and glucose metabolism, and the biology of aging itself." (PMID 39590829, 2024). "In this study protocol, the aim is to examine insulin-stimulated GU in conjunction with low-grade inflammation with or without exercise intervention in an HFD-induced rat model of obesity." (PMID 38651416, 2024). "This study assessed the potentials of seaweed-derived sulphated polysaccharides (SPs) to modulate obesity-related parameters, including food intake, body weight gain, lipid accumulation, inflammation, insulin resistance, hepatic injury, and lipid profiles." (PMID 39728103, 2024). "This modulation is achieved through direct effects on insulin signaling pathways and indirect effects via improving obesity phenotypes." (PMID 39272602, 2024). "When considering the outcomes among all groups, the most prevalent comorbidity was obesity, and the second most pervasive was insulin use." (PMID 38667608, 2024). "A different study investigating the effect of consumption of fermented kimchi on obesity in South Korean women reported improvements in waist-hip ratio, blood pressure, insulin, and fasting blood glucose in participants who consumed 300 g of FVs per day." (PMID 39290661, 2024). "Insulin sensitivity was lower in the morbid obesity/obesity group in comparison with the normal-BMI group initially and annually, as evidenced by insulin, HbA1C, and HOMA-IR levels." (PMID 39339733, 2024). "An early diagnosis of Type 2 diabetes, which is closely tied to obesity and high endogenous insulin, is also predictive of earlier menopause." (PMID 38131197, 2024). "The cross-sectional study by Norris AL who investigated 225 children adolescents with normal weight, overweight, obesity, and severe obesity revealed that values of BP, and the levels of insulin, and lipids worsened with the higher BMI." (PMID 38877324, 2024). "It has been documented that C57BL/6J mice remain more insulin sensitive than other strains despite higher weight gain in response to diet-induced obesity." (PMID 39120469, 2024). "In this study, we characterized a new mechanism by which fetuin-A downregulation contributes to the beneficial effects of apigenin on obesity-induced dysregulation of insulin signaling in hepatocytes and the liver." (PMID 38481798, 2024). "The obesity was accompanied by impaired glucose and insulin tolerance, together with high levels of fasting insulin in the circulation and fatty liver." (PMID 38762479, 2024). "By regulating glucose and insulin levels, IF can contribute to the management of glycemic profiles and obesity." (PMID 39044934, 2024). "Several clinical trials and animal studies have demonstrated that supplementation with ketogenic amino acids can have a positive impact on insulin sensitivity and/or obesity." (PMID 39056704, 2024). "Increased SREBP-1c expression has been demonstrated to be associated with high-fat or high-fructose diet feeding, high insulin levels or IR state, obesity, and MASLD." (PMID 39351533, 2024). "The associations between central TH sensitivity and hepatic and whole-body insulin sensitivity need to be explored in future studies with larger samples and more general populations than just people with obesity." (PMID 39175570, 2024). "This study, independent of genetic factors in monozygotic twins discordant for BMI, aimed to examine the effects of obesity on insulin-stimulated liver glucose uptake, LFC, PFC, and pancreatic beta-cell function." (PMID 39334836, 2024).
Obesity (continued). "Obesity manifests as a condition characterized by chronic inflammation and elevated levels of insulin, lipids, and leptin." (PMID 38892653, 2024). "Several recent studies have demonstrated that IL-36 cytokine expression is elevated among adult patients with obesity, and can play roles in regulating both insulin sensitivity and driving inflammation." (PMID 38467728, 2024). "On the other hand, IL-6 is elevated in obesity and with exercise, and thus, its effects on insulin signaling are controversial." (PMID 38999834, 2024). "Conversely, FGF21 treatment improved hepatic and whole-body insulin sensitivity in a mouse model of diet-induced obesity." (PMID 38732106, 2024). "The role of PGRN in obesity-related disorders has been recently described, showing its higher levels in obesity and insulin-resistant state in the majority of studies." (PMID 39139157, 2024). "At the same time, obesity hastens the onset of atherosclerotic alterations via a range of pathways, such as insulin resistance and inflammatory processes." (PMID 39866802, 2024). "We also identified the gene atp10d (Phospholipid-transporting ATPase VD), which has been shown to improve insulin sensitivity and reduce the chance of developing obesity in mice fed a high-fat diet." (PMID 39151124, 2024). "In the context of obesity, factors such as the insulin and IGF axis, sex hormone concentrations, and altered adipokine signaling can enhance cancer cell proliferation." (PMID 38817878, 2024). "In an obesity model, it has been seen that the cephalic phase of insulin release, impaired in obesity, is modulated by IL-1β originating from microglia." (PMID 39595866, 2024). "As in individuals with obesity, the levels of adiponectin, insulin, ghrelin, and leptin are disrupted, and the same molecules affect the regulation of the hypothalamic–pituitary–gonadal axis (HPG), impacting the timing of puberty." (PMID 39203868, 2024). "These outcomes not only provided scientists with additional knowledge about the physiological roles of insulin in metabolism and body weight regulation, but also paved the way for the ongoing advances in anti-obesity medications." (PMID 39544693, 2024). "In fact, the increase in insulin secretion induced by obesity, along with a decrease in insulin clearance, is sufficient to explain the increase in plasma insulin concentrations needed to maintain normoglycemia." (PMID 38942960, 2024). "Evidence indicates that acetate is linked to obesity, with elevated acetate levels generated by the gut microbiota activating the parasympathetic nervous system, promoting insulin secretion, and leading to hyperphagia and obesity in rodents." (PMID 39439902, 2024). "Despite the similar anti-obesity effects in knockout and overexpression models, PLIN1 adipose overexpression enhances glucose tolerance and insulin sensitivity, but its deficiency causes the opposite effects in mice." (PMID 39030618, 2024). "In individuals with obesity‐related IR, the pancreas also undergoes several changes, which can impact insulin secretion and function." (PMID 38812572, 2024). "This difference in insulin sensitivity plays a significant role in the systemic effects of obesity, particularly the development of insulin resistance." (PMID 38474344, 2024). "Decreased insulin sensitivity contributes to increased food consumption, impulsive eating and obesity." (PMID 38201978, 2024). "This review and meta-analysis suggest that adhering to a plant-based diet for at least 14 d can improve markers of insulin sensitivity in people with overweight/obesity." (PMID 38999858, 2024). "Insulin-stimulated glucose oxidation was significantly higher in myotubes from lean donors than donors with severe obesity (P < 0.05)." (PMID 38324260, 2024). "A special ceramide, C16:0, has been identified as a key negative regulator of FAO and insulin sensitivity in obesity." (PMID 38456906, 2024).
Obesity (continued). "Exercise is a stimulator that promotes the browning of WAT, accelerates glycolipids, decreases the insulin requirement and suppress the occurrence and development of obesity." (PMID 39590824, 2024). "Hyperinsulinemia is a normal physiological state during puberty, but children with obesity can have abnormally high fasting blood insulin (FBI) levels." (PMID 38670169, 2024). "Ruminococcaceae exerts a regulatory influence on lipid metabolism, diminishes inflammation, fortifies intestinal barrier integrity, curbs weight gain, and enhances insulin sensitivity in mice, effectively impeding the progression of obesity." (PMID 38807189, 2024). "IR refers to the diminished efficacy of insulin in influencing its target tissues, commonly observed in individuals with metabolic disorders such as obesity." (PMID 39104778, 2024). "Comparable effects were also observed among 20 insulin-resistant women with obesity, where a high-protein diet was more effective in reducing glycemic variability, compared with a Mediterranean diet, in a 21-day trial." (PMID 39145315, 2024). "Dysregulation of lipolysis and insulin sensitivity in obesity often correlates with increased systemic inflammation." (PMID 38470490, 2024). "Several metabolic pathways are involved in the progression of metabolic abnormalities during the development of obesity, leading to changes in adipose tissue inflammation, insulin resistance and adipogenesis." (PMID 39771046, 2024). "In the pancreatic β-cell, the elevated FFAs in plasma during obesity will result in the sustained activation of JNK, which, in turn, negatively regulates insulin secretion and finally causes β-cell dysfunction and death." (PMID 38397480, 2024). "Studies have also reported that patients with obesity who are insulin sensitive have a low degree of liver steatosis compared with those who are obese and insulin resistant, which is a pattern that persists in follow-up assessment." (PMID 38656127, 2024). "Obesity-related changes in insulin and bioavailable IGF-1 have been shown to stimulate ovarian androgen synthesis." (PMID 38213908, 2024). "Since adiponectin is also considered to have insulin sensitivity-promoting, anti-inflammatory, and anti-atherogenic properties, there is great interest in increasing its expression in obesity and chronic inflammatory conditions." (PMID 38605957, 2024). "These functions encompass insulin sensitivity, glucose homeostasis, energy balance, obesity, and the levels of metabolic hormones." (PMID 39138413, 2024). "In contrast, the DCCT study (n = 507, aged 8–16 years) demonstrated a relatively stable prevalence trend of overweight/obesity from 1999 (~27%) to 2009 (~31%), despite the increasing implementation of intensive insulin therapy (~52 to ~97%)." (PMID 38092958, 2024). "The GHR-KO pig particularly resembles the phenotype of Ecuadorian LS patients, where a preserved glucose tolerance despite decreased insulin secretion capacity results from an increased insulin sensitivity despite obesity." (PMID 38960990, 2024). "Important inputs for their models include age, resistin levels, global burden of disease (GBD) relative risk upper values, glucose, adiponectin, high BMI (binary), MCP-1, leptin, relative risks from meta-analyses, obesity (binary), and insulin levels." (PMID 38699635, 2024). "It has been shown that physical obesity and metabolism of steroid hormones, response to inflammation, and insulin regulation can influence PSA expression." (PMID 37340224, 2024). "Generally, the pro-inflammatory factor IL-6 regulates adipocyte production and counteracts obesity, but its role in insulin sensitivity remains controversial." (PMID 38982993, 2024). "Knockout of Ramp3 in ovariectomized mice showed elevated serum insulin levels accompanied by exacerbation in obesity, adipocyte hypertrophy, and adipose tissue weight gain." (PMID 38931172, 2024).
Obesity (continued). "AT-exos have been proven to play a regulatory role in the sensitivity of the body to insulin through multiple signaling pathways and are strongly correlated with individual obesity." (PMID 39220365, 2024). "Obesity and type 2 diabetes have been shown to deteriorate insulin-stimulated intestinal glucose uptake (intestinal uptake of circulating glucose from blood)." (PMID 39458548, 2024). "These individuals often display heightened insulin sensitivity, which contributes to the development of obesity and an elevated body mass index (BMI)." (PMID 38792950, 2024). "We end by summarizing the effects of BCAA supplementation or restriction on obesity and insulin sensitivity." (PMID 39007094, 2024). "High levels of IL‐18 in PCOS patients were found to be correlated with insulin sensitivity and obesity." (PMID 39036884, 2024). "Even short-term high intensity training increases cellular insulin sensitivity, and intensifies glucose and fat oxidation, particularly beneficial for individuals with obesity and T2D." (PMID 39376657, 2024). "Studies using in vivo models of obesity have shown a correlation between decreased miR-26 expression and impaired insulin and glucose levels." (PMID 39684879, 2024). "Knockout mouse models lacking TNF-α function show improved insulin sensitivity and glucose homeostasis, highlighting TNF-α′s role in modulating insulin action in obesity." (PMID 38606081, 2024). "Beyond the well-known links between PCOS, obesity, and metabolic syndrome, gonadal functions, and insulin sensitivity exhibit complex relationships." (PMID 38671256, 2024). "The dysregulated of glucose metabolism in obesity results from by both the inadequate increase in insulin secretion through the numerical incretin effect and insufficient suppression of glucagon secretion." (PMID 38966210, 2024). "Insulin-regulated regional free fatty acid metabolism is impaired in upper-body obesity during moderate hyperinsulinemia, especially in upper-body subcutaneous adipose tissue." (PMID 38602778, 2024). "SHS exposure has been shown to alter hormone levels, such as leptin and insulin, which regulate appetite and energy balance, thereby promoting weight gain and obesity in children." (PMID 39457215, 2024). "Previous studies have reported that autophagy directly impacts insulin tolerance, hepatic triglyceride levels, and obesity." (PMID 38237682, 2024). "It has been shown that Ghr global null mice exhibit dwarfism, severe postnatal growth retardation and obesity, but with greatly enhanced insulin sensitivity." (PMID 39623508, 2024). "Based on nine laboratory variables, they identified five clusters, among others an insulin resistant–hyperglycemic cluster that had the highest rates of obesity in the offspring." (PMID 39081793, 2024). "Adipose exclusively secretes adiponectin, an adipokine which reduces triglycerides levels and controls insulin signalling, whose levels are decreased in obesity." (PMID 38248845, 2024). "Maternal nighttime eating is associated with higher infant adiposity at 6 months of age, independently of maternal obesity, use of metformin or insulin, energy intake in pregnancy, and exclusive breastfeeding." (PMID 39050138, 2024). "Obesity is characterized by a range of pathological mechanisms, including lipid metabolism disorders, oxidative stress, chronic low-grade inflammation, insulin resistance, endocrine disturbances, and abnormal nervous system regulation." (PMID 39200098, 2024). "Stress has been reported to induce glucocorticoids, which stimulate food intake, and insulin, which promotes obesity." (PMID 39723262, 2024). "Resveratrol improves insulin action in primary human skeletal myotubes derived from lean women and women with severe obesity." (PMID 38324260, 2024). "To explain the exacerbation of OS in obesity, we conducted insulin concentration studies during the OGTT, extending it to 240′ minutes." (PMID 38655176, 2024).